KRAS (KRas proto-oncogene, GTPase)
Diseases named in the same sentence as KRAS in open-access papers (continued):
Sharing a sentence is not in itself a finding about the gene and the disease.
tumor (continued). "Of note, in addition to methodological issues, the intratumor heterogeneity also matters the concordance rate of KRAS mutations between cfDNA and tumor tissues, with different areas of the same tumor showing different genetic profiles." (PMID 30791218, 2019). "In cases with MAF < 1% by OncoBEAM, plasma mutational analysis was also compared to tissue-based methods on paired primary tumor specimens in order to independently examine the clinical sensitivity of Idylla and OncoBEAM plasma KRAS mutation detection." (PMID 31222012, 2019). "Lastly, the work suggests that tumor stratification by co‐mutations to KRAS/NF1 highlights the LAUD patient population expected to benefit from inhibiting PSAT1." (PMID 31036704, 2019). "In conclusion, we confirmed that the KRAS mutations identified from CRC tumor tissue samples were consistently detected in the plasma cfDNA of the three CRC patients by dPCR." (PMID 31896242, 2019). "The mutational status of KRAS is also highly concordant between primary tumor formation and metastasis, suggesting a role in the early process of carcinogenesis." (PMID 31816869, 2019). "KRAS mutation detection has also been performed on circulating cell free tumour DNA and on isolated exosomes." (PMID 31248203, 2019). "In contrast, the frequency of KRAS mutations in LUAD seems constant across tumor grades, suggesting a role in tumor initiation or early tumorigenesis." (PMID 31889956, 2019). "Although this study showed the different KRAS status in RCC and LCC, and found the prognostic value of KRAS mutation was depending on the location of tumor, there were several limitations should be considered when interpreting the results." (PMID 30917791, 2019). "CMS3 tumours (13%) display epithelial feature and metabolic dysregulation and include most KRAS-mutated tumours." (PMID 31091767, 2019). "They found significantly increased number of tumor-associated neutrophils (TAN) and decreased number of tumor-associated macrophages (TAM) in KL tumors compared to tumors showing alterations only in KRAS (K)." (PMID 30995715, 2019). "Thereby, we found the same KRAS-G12C mutation (c.34G>T) detected in the tumor biopsy of one patient at initial diagnosis also in the DNA from six CTCs isolated from that patient by the microfluidic system." (PMID 31212989, 2019). "KRAS mutations are also associated with a poorer outcome, but this association is stronger in distal compared to proximal tumours." (PMID 31775679, 2019). "In an attempt to overcome this shortcoming, the current study was corrected for right-sidedness of the primary tumour, which is associated with KRAS and BRAF mutational status." (PMID 30637550, 2019). "The KRAS status was identified in only 143 patients and KRAS mutations were observed in 52 (36.4%) tumor tissues." (PMID 31703307, 2019). "It is reported that KRAS is one of the most frequently mutated genes in PC, with a detection rate in tumor tissue ranging from 75 to 95%." (PMID 31850201, 2019). "A positive medial resection margin and a higher frequency of KRAS mutation in tumour tissue are independent prognostic indicators for resectable PDAC." (PMID 30774772, 2019). "The tumor-initiating oncogenic KRAS mutations, which are found in >90% of PDAC cases, initiate the process for noninvasive precursor lesions." (PMID 31769422, 2019). "Other factors, such as format of blood samples, storage method of tumor tissues, and detection methods of KRAS mutations, also matter the limited generalizability." (PMID 30791218, 2019). "Oncogenic KRAS has been shown to corporate with LKB1 loss to induce the serine–glycine–one-carbon pathway to fuel tumor growth." (PMID 31569510, 2019).
tumor (continued). "Genomic DNA was isolated from whole blood for the analysis of VEGF-A (rs2010963, 1570360, rs699947), ICAM-1 (rs5498, rs1799969) SNPs and from tumor tissue for the detection of genomic variants in KRAS, NRAS, BRAF genes." (PMID 31752122, 2019). "In contrast, there was a significant interaction between treatment group and KRAS mutation status as regarding the tumor response (p = 0.03)." (PMID 30736475, 2019). "RAS mediated signalling is well studied, as somatic mutations in KRAS are found commonly in tumours whereas mutations in HRAS and NRAS are found with much lower frequency." (PMID 31160609, 2019). "Tumor characterization revealed that 17 patient tumors were positive for KRAS mutations, of which six (35.3%) were G12V mutations and 11 (64.7%) were G12D." (PMID 31383871, 2019). "Detailed examination of the KRAS mutations calls in the primary tumour series revealed the presence of G12D, G12R, and G12V oncogenic mutations, with the majority of missense mutations belonging to G12D." (PMID 30629588, 2019). "Below, we discuss the latest discoveries on the communication between mutant KRAS cancer cells and their microenvironment, emphasizing those that hold clinical potential for the tumor types where KRAS mutations are frequent." (PMID 31847096, 2019). "The anti-EGFR therapy in metastatic patients is led by the presence of KRAS-mutations in tumor tissue." (PMID 31673240, 2019). "KRAS mutation status of the primary tumor was then determined by amplicon-based targeted deep sequencing using the Illumina TruSight Tumor 15 panel." (PMID 30611220, 2019). "In 67 tumor tissues, discrepancies in point mutations of KRAS were rarely observed among individual patients, implying that one targeted point mutation of KRAS can be determined in tumor tissues prior to longitudinal blood monitoring." (PMID 31891652, 2019). "We identified that tumour samples from those with early recurrence had a higher frequency of KRAS mutation than from those with late recurrence." (PMID 30774772, 2019). "The percentage of the primary tumor-specific KRAS mutation in pancreatic juice was then used as a surrogate measure of the amount of ctDNA." (PMID 30611220, 2019). "Tumour samples from all patients were screened for known hotspot mutations in KRAS, BRAF and NRAS as part of routine diagnostic examination." (PMID 31395942, 2019). "In tumor tissue, KRAS or BRAF mutations were present in 35 of 65 cases (44% UICC stage I, 50% stage II, 47% stage III, and 62% stage IV)." (PMID 31134762, 2019). "A further study demonstrated that the presence of KRAS mutations in ctDNA was related to disease progression, particularly in the WT tumor patients treated with anti-EGFR therapy." (PMID 31824558, 2019). "In the data, KRAS mutation signature of the CRCs (p.G12D) correlated with the KRAS mutation found in the patient's primary tumor (p.G12D)." (PMID 31044541, 2019). "Medial resection margin status and the frequency of KRAS mutation in the tumour tissue are independent prognostic indicators for resectable PDAC." (PMID 30774772, 2019). "Similar results were observed for the IHC classification: 60.7% of the Ang-PB tumours had KRAS, mutations versus 32.5% of the Ang-INT tumours (p < 0.02)." (PMID 30837681, 2019). "Further molecular analysis showed that the KRAS mutation was detected in plasma samples and tumor tissues." (PMID 31852167, 2019).
tumor (continued). "In patients without treatment benefit (n = 13), four BRAF p.V600E mutations and one rare KRAS p.G60D mutation were detected in tumor tissue." (PMID 31350822, 2019). "Tumour cells with BRAF (most frequently BRAFV600E) or KRAS mutations are addicted to MEK1/2 (MAPK or ERK Kinase)–ERK1/2 (extracellular signal-regulated kinase) signalling for their proliferation, survival and other malignant properties." (PMID 31048689, 2019). "The detection of ctDNA in urine samples from CRC patients using NGS has been associated with tumor load, while the comparison between tumor tissue and urine mutant KRAS was highly concordant." (PMID 31623125, 2019). "Increased IFN-γ production to the mutated KRAS peptide KLVVVGAVGVGKSAL (representing the well-described KRASG12V mutation) was observed after 3× stimulation with the autologous tumour cell-stimulated TILs compared to young TILs." (PMID 30377343, 2019). "We found that a patient with KRAS p.Gln61 mutation at a very low allelic frequency in the tumor tissue and a liquid biopsy positive for the same KRAS variant had a quite short PFS." (PMID 31226844, 2019). "Lastly, the findings advocate that tumor stratification by co‐mutations to KRAS/NF1 highlights the LAUD patient population expected to be susceptible to inhibiting PSAT1." (PMID 31036704, 2019). "The T5 patient whose tumor had 90% wildtype KRAS despite the presence of the KRASG12V mutation was treated with Bevacizumab to target VEGFR, a common target in mCRC, but deceased 10 months after diagnosis." (PMID 31805664, 2019). "The test identified 69 patients (33%) with detectable mutant KRAS genes in their plasma (out of 79 patients with KRAS mutation present in the tumour), which yielded a sensitivity of 87.2% with respect to cancer detection." (PMID 30677217, 2019). "As our cultures contain only tumor cells based on the allele frequency found for the KRAS mutation and the homogenous positivity of the whole cultures in IF stainings, our data nevertheless argues for existence of this PDAC subtype." (PMID 31191661, 2019). "Similar to the association pattern seen in TCGA survival data, in vivo tumorigenesis by KRAS-dependent human tumor cells in immune deficient mice required SNAP23 and VAMP3, but not SNAP29." (PMID 31712554, 2019). "BRAF and KRAS are mutually exclusive, and 1 tumour harboured a double mutation in the BRAF and NRAS genes." (PMID 30837681, 2019). "It is important to point out that the combination of the enhanced Wnt pathway with a constitutive activation of different molecular pathways (such as the KRAS pathway) caused by the mutations in KRAS triggers an increase in tumor size and a poor prognosis." (PMID 31608072, 2019). "(i) Similarly to other oncogenic lesions, the effect of KRAS mutations in metabolic adaptation can differ in distinct tumor types depending on the tissue of origin." (PMID 31544066, 2019). "Examples are oncogenic KRAS mutations, which tumor-intrinsically inhibit HH signaling but simultaneously activate it in the tumor microenvironment." (PMID 31867038, 2019). "It is well known that Type I tumours are genetically stable and are characterized by mutations in a number of different genes including KRAS, BRAF, PTEN, and beta-catenin." (PMID 31569439, 2019). "Tumour grading, organ metastasis, and KRAS mutation in the primary tumour were detected and compared between the studied groups." (PMID 31467552, 2019). "Among the 31 studies, 19 used formalin‐fixed paraffin‐embedded (FFPE) tumor tissues to detect KRAS mutation status." (PMID 30791218, 2019). "The choice of the most cost-effective method for somatic tumor mutations detection, including KRAS, is a major challenge for molecular pathology laboratories." (PMID 30949599, 2019).
tumor (continued). "A better understanding of the tumor biology and predictive factors is crucial for the identification of new therapeutic targets in KRAS-mutated CRC patients." (PMID 31673240, 2019). "The BRAF gene was mutated in 8 tumor samples (8.8%), showing 8 missense somatic mutations mutually exclusive with KRAS, all previously reported as somatic mutations in CRC." (PMID 31548566, 2019). "We first evaluated KRAS mutation status in the primary tumor by Sanger sequencing, a technique which has a limited sensitivity for detection of somatic mutations." (PMID 30611220, 2019). "KRAS mutations are abnormalities widely found in genomic DNA and circulating tumor DNA (ctDNA) of various types of cancers." (PMID 30976068, 2019). "KRAS/NRAS mutations are common in ICC tumours and 6–32% of patients also have isocitrate dehydrogenase 1 and 2 (IDH1 and IDH2) gene mutations associated with metabolic changes." (PMID 31795195, 2019). "The copper (Cu) dependence of MEK1/2 dysfunctional signalling is an important target to inhibit tumour cells with BRAF or KRAS mutations." (PMID 30792807, 2019). "Idylla ctKRAS and OncoBEAM plasma testing results were compared with KRAS mutation results obtained by SOC FFPE tumor tissue testing in 43 mCRC patients that were OncoBEAM KRAS-MUT+ with MAF values <1%." (PMID 31222012, 2019). "Neurothropic tyrosine receptor kinase B (TrkB) is a potent anoikis suppressor, which is overexpressed in tumor buds and in CRC with high-grade tumor budding and KRAS mutations." (PMID 31803624, 2019). "The majority of studies have assayed for KRAS mutations, or other mutations personalized to the tumor tissue." (PMID 31824558, 2019). "In conclusion, we confirmed that the KRAS mutations identified from the CRC tumor tissue samples were consistently detected in the plasma cfDNA of the three CRC patients by dPCR." (PMID 31896242, 2019). "The PCR-rSSO method detects perfectly-matched mutated alleles in tumor samples; therefore, it missed the KRAS multi-nucleotide variant, c.180_181delTCinsAA, and reported this site as wild type." (PMID 31711486, 2019). "Whereas, among the eight patients with metastatic CRC bearing tumor-associated KRAS mutations, the diagnostic sensitivities before and after the enrichment assay were not significantly different (100% vs. 75.0%, P = 0.47)." (PMID 31383871, 2019). "Further analyses revealed that therapeutic benefit of combined gemcitabine/EGFR inhibition associated with KRAS wild‐type tumour status 179, 180 or development of skin rash in patients, which represents another measure of EGFR inhibitor activity." (PMID 31330086, 2019). "Nevertheless, noteworthy differences in the incidence of KRAS exon 2 mutations among tumour locations have been reviewed." (PMID 30683047, 2019). "In 13/14 cases with available tumour or plasma samples the presence of the KRAS mutation was confirmed using ddPCR." (PMID 30857358, 2019). "The detection of KRAS mutation in ctDNA was performed using droplet digital PCR and compared with that in matched tumor tissue." (PMID 31850201, 2019). "All variants were at an allelic frequency >5% with the exception of a KRAS variant (c.183A>T; p.Gln61His) that was identified in the tumor tissue from patient P7 (PFS 3.93 months) at an allelic frequency of 0.4%." (PMID 31226844, 2019). "The adoptive transfer of T-cells harbouring the engineered T-cell receptors (TCR) that specifically recognise mutated KRAS variants G12V and G12D has also been proven effective in reducing tumour growth in a KRAS mutant xenograft model." (PMID 31438559, 2019). "Five (10.4%) and 31 (64.6%) patients presented BRAF mutations and KRAS mutations in at least one tumor, respectively." (PMID 31324877, 2019).
tumor (continued). "Treatment with the PPP inhibitor 6-aminonicotinamide (6-AN) abrogated the growth of Keap1-deficient tumor cells, suggesting a potential therapeutic approach to target this subset of KRAS-mutant LUAD cancers." (PMID 31519898, 2019). "When we examined the three KRAS mutations by dPCR using tumor tissue samples, all of them were consistently detected and the variant allele frequencies (VAFs) of the mutations were almost identical between targeted NGS and dPCR." (PMID 31896242, 2019). "The genetic landscape of the tumor cooperates with KRAS mutations in the elevation of glycolysis to promote cancer growth and dissemination." (PMID 31544066, 2019). "Molecular analysis showed that the KRAS p.G13D mutation was detected in plasma samples and tumor tissues." (PMID 31852167, 2019). "Intratumoral heterogeneity of KRAS, in which multiple alleles of the oncogene exist within an individual tumor, can lead to the misdiagnosis of tumors as wild-type RAS." (PMID 31247990, 2019). "Most studies have applied the detection of the KRAS oncogene mutation to identify circulating tumour DNA." (PMID 31248203, 2019). "In CRC, KRAS mutations status and tumor location are associated with targeted therapy effectiveness." (PMID 30917791, 2019). "Circulating tumor cells (CTCs) were detected using the CellSearch® method or after RosetteSep® enrichment combined with CRISPR/Cas9-improved KRAS mutant alleles quantification by droplet digital PCR." (PMID 31717747, 2019). "Tumor that origins from the two sites of the colon has different molecular carcinogenic characters, including KRAS, BRAF mutations and microsatellite instability (MSI)." (PMID 30917791, 2019). "Nevertheless, our study suggests that specific KRAS mutation subtypes can have a major impact on tumor vascularization and, potentially, on the response to anti-angiogenic treatment." (PMID 31600989, 2019). "Eighteen (40.0%) MCRC patients showed a KRAS mutation in at least one tumor and 11 (24.4%) in paired-tumors." (PMID 31324877, 2019). "Somatic mutations in the genes encoding VEGFR2, FGFR1, FGFR2, FGFR3, and KRAS were identified in the patient's tumor tissue." (PMID 30792968, 2019). "It has been demonstrated that, among CRC patients with point mutations in exon 2 (codons 12 and 13) or exon 3 of KRAS, prognosis is worse only in those having a distal tumor." (PMID 30736475, 2019). "Cell-free circulating tumor (ct) DNA was measured as either the fraction with Neuropeptide Y (NPY) methylated DNA or KRAS/NRAS/BRAF mutated ctDNA." (PMID 31731482, 2019). "Here the authors use an in vitro stimulation approach to isolate tumor specific memory T cells from peripheral blood of metastatic epithelial cancer patients targeting unique as well as shared mutations in the KRAS oncogene." (PMID 30683863, 2019). "Discrepancies in point mutations of KRAS were rarely observed among individual patients, implying that a targeted point mutation of KRAS can be determined in tumor tissues prior to longitudinal monitoring of blood." (PMID 31891652, 2019). "Sequence analysis of KRAS point mutation in EBC–DNA revealed the same sequence as in the corresponding tumor harboring this mutation (n = 12)." (PMID 30368666, 2019). "Some studies also reported that the prognostic utility of KRAS mutation in ctDNA and in tumor tissue was discordant." (PMID 31850201, 2019). "In one case of NSCLC with intratumor heterogeneity of KRAS mutation EBC–DNA sequence was the same as one of the two coexistent sequences in tumor tissue." (PMID 30368666, 2019). "As KRAS was the most commonly detected mutation, we compared the concordance of ctDNA and tumor tissue in detecting KRAS mutation in metachronous and synchronous groups." (PMID 29707525, 2018).